PRL (prolactin)
Diseases named in the same sentence as PRL in open-access papers (continued):
Sharing a sentence is not in itself a finding about the gene and the disease.
Galactorrhea (continued). "None of the patients had prolactin-related complaints or symptoms, such as menstrual irregularity, galactorrhea, or erectile dysfunction." (PMID 27169416, 2016). "The groups had similar baseline characteristics, the mean follow up was 3.5 years and the main outcomes were normal prolactin levels, normal menstrual cycle, no galactorrhea, visual field improvement, operative time, hospital stay and complications." (PMID 27598981, 2016). "The pathophysiologic mechanisms responsible for a gynaecomastia with/without galactorrhea in thyrotoxicosis are a result of the increase in the physiologically active estrogen to androgen ratio and are not related to changes in prolactin secretion." (PMID 28044109, 2016). "Guidelines pointed out that routinely prolactin determinations can be avoided in patients without symptoms (gynecomastia, galactorrhea, and amenorrhea)." (PMID 27209326, 2016). "Major drawbacks of our study were not being able to measure multiple prolactin levels with and without stimulatory cues and not performing MRI scan of pituitary during the period of galactorrhoea." (PMID 25518745, 2014). "No galactorrhea or other clinically important prolactin-related adverse events were reported in this study." (PMID 22903391, 2013). "Due to the transient nature and spontaneous resolution of galactorrhea in this patient, further prolactin levels were not obtained at that time." (PMID 19852783, 2009). "Quetiapine's use is acceptable when galactorrhoea does not emerge, and patients' are likely to accept it even if prolactin is elevated." (PMID 17650327, 2007). "A randomized study in Turkey showed that cohorts on quetiapine had no prolactin elevation while two of those on haloperidol had galactorrhoea." (PMID 17650327, 2007). "It appears that galactorrhea is a benign side effect and as previous reports have suggested, it did not seem to be related to changes in Prolactin levels in our patients." (PMID 16680366, 2006). "Although the patient had a high serum level of PRL, galactorrhea did not occur." (PMID 41321897, 2025). "In the present study, transient prolactin elevation was the second common event and found in 12 of 57 patients in the 5 μg group, 5 of 57 in the 2.5 μg group and 2 of 27 in the placebo group, although gynecomastia and galactorrhoea were not reported." (PMID 36856148, 2023). "In our sample, we found 5 cases of galactorrhea without elevated levels of prolactin." (PMID 33768297, 2021). "On the other hand, a probable alternative explanation for the absence of galactorrhea may be heterogeneity of prolactin molecules." (PMID 26091810, 2015). "No prolactin-related clinical symptoms (e.g., galactorrhea) were observed." (PMID 22903391, 2013). "As seen in previously reported cases, galactorrhea may also be promoted by stopping oral contraceptive pills a few days before the procedure; the estrogen hormone concentration is no longer sufficient to block the action of PRL." (PMID 39974504, 2025). "Furthermore, some patients may have clinical features of concomitant hypersecretion of other pituitary hormones such as acromegaly or galactorrhea/amenorrhea, as about one-quarter of TSH-omas have been found to cosecrete other pituitary hormones, most commonly growth hormone and prolactin." (PMID 41573500, 2025). "Consistent with the improvements in prolactin levels, after adjunctive aripiprazole treatment, 37 participants with menstrual disturbances regained menstruation, 17 patients no longer complained of signs or symptoms of galactorrhea in two studies, whereas no patients did so in the placebo group." (PMID 23936389, 2013). "Independently of the nature of big big PRL (i.e., due or not to anti-PRL autoantibodies), clinical symptoms of HPRL, such as amenorrhea and galactorrhea in women and impotence in men, are usually less frequent or even absent in patients with MPRL." (PMID 24194758, 2013).
Obesity (125 papers, 2010 to 2026). Accumulation of substantial excess body fat. "PrRP and GPR10 deficient mice are at high propensity to develop obesity and IR due to lowering of circulating PRL level." (PMID 39663784, 2024). "this study has shown the factors associated with ORR in our setting to be basal FSH, prolactin, and obesity." (PMID 39092016, 2024). "Low-normal PRL levels, distinct from hypopituitarism, were found to be associated with type 2 diabetes, metabolic disease and in children with obesity which is reversed after weight loss." (PMID 38700812, 2024). "Consistent with previous reports in rats, diet-induced obese mice had lower levels of PRL than lean mice, which indicates that an imbalance in PRL levels is associated with disrupted metabolic homeostasis under obesity." (PMID 38635745, 2024). "In this review, potential molecular mediators of FMC associated with obesity are discussed, including leptin, adiponectin, serum amyloid A, estrogen, and prolactin." (PMID 37626804, 2023). "In our study which enrolled patients with men whose BMI was less than the criteria of obesity, the results also showed that PRL was significantly negatively associated with TCH in men with T2DM." (PMID 36313749, 2022). "While it is recognized that significantly elevated prolactin levels are associated with weight gain, obesity, and overall metabolic dysfunction, the metabolic effects of prolactin vary even within a physiologic range." (PMID 36246929, 2022). "In subjects with obesity, moderately high PRL levels associate with lower levels of interleukin 6 in children and tumor necrosis factor-α (TNF-α) in adults." (PMID 36213259, 2022). "The pathogenesis of obesity and alterations in glucose profile have been linked to PRL excess, as it is reportedly associated with metabolic syndrome in thereabout one third of patients." (PMID 31191454, 2019). "Common human variation in IGSF1 is associated with age at menarche, and loss-of function mutations cause a human syndrome of congenital hypothyroidism, macroorchidism, Prolactin and Growth Hormone deficiency, delayed pubertal testosterone and obesity." (PMID 27503363, 2016). "Two recent studies showed that rs4712652 SNP near the PRL gene showed association with BMI and risk of obesity." (PMID 24667351, 2014). "Lower prolactin levels may reflect underlying metabolic health and may be relevant to the suboptimal lactation outcomes observed in women with obesity and metabolic disease." (PMID 42157583, 2026). "In contrast, obesity may be associated with increased circulating prolactin levels, which are potentially mediated by adipose tissue expansion, enhanced aromatase-dependent estrogen production, and chronic low-grade systemic inflammation." (PMID 41918976, 2026). "However, reduced prolactin response to suckling has been linked to lower lactogenesis and early lactation failure in women with obesity." (PMID 39857075, 2025). "Interestingly, hsa-miR-329-1-5p, which in our study was linked to metabolic disturbances, also participates in metabolic pathways—including prolactin signaling and cholesterol metabolism—whose dysregulation has been implicated in obesity." (PMID 41614784, 2025). "Of note, MetS, obesity and T2D are associated with significant reduction of circulating PRL level." (PMID 39663784, 2024). "These metabolic favorable mechanisms become disrupted under insulin resistant and obesity conditions, which is associated with low circulating PRL levels and could be counteracted by increasing PRL levels." (PMID 36993818, 2023). "Notably, extremely high or deficient PRL levels can lead to detrimental metabolic alterations, such as obesity, MS, and disruptions in glycemic and lipid profiles." (PMID 38004264, 2023). "In this context, deciphering prolactin action, and the effect of prolactin antagonism on brown adipocytes may yield valuable tools in the effort to curtail obesity or accelerate weight loss." (PMID 35757410, 2022).
Obesity (continued). "Previously it was shown that there is a positive association between PRL and obesity." (PMID 34660034, 2021). "Maternal overweight or obesity are also reported to be risk factors for delayed stage II lactogenesis due to a decreased prolactin response to infant suckling, which may cause breastfeeding difficulty and a lower rate of breastfeeding continuation." (PMID 31384287, 2019). "Therefore, obesity and/or higher glucose levels (or glycemic levels) seem to influence the observed association between serum PRL levels and HOMA-R." (PMID 28384295, 2017). "In summary, our findings reveal a novel mechanism responsible for reduced lactation success in obesity, and they support a model in which high leptin levels are a possible cause of the peripheral and central prolactin resistance that is observed in obese animals." (PMID 26926925, 2016). "In addition, the obesity-related risk allele (A) of SNP rs4712652 in the PRL gene was associated with a lower 2-h glucose level during the OGTT and a higher level of β cell function." (PMID 25093408, 2014). "In women with obesity, the mammary gland undergoes structural and endocrine changes, such as reduced prolactin secretion, fewer mammary gland branches, and a higher abundance of adipocytes in mammary fat pad, which have not been studied under this condition." (PMID 41750272, 2026). "At the same time, obesity dampens the prolactin response to suckling—a pivotal hormonal signal for lactogenesis—which is compounded by prolonged progesterone exposure and increased local estrogen production due to enhanced aromatization in adipose tissue." (PMID 40868103, 2025). "Both clinical observations and animal models have provided evidence that obesity induces central and peripheral prolactin resistance." (PMID 40868103, 2025). "The need for gender-specific thresholds in particular arises from inherent differences in PRL levels between males and females, compounded by the varying impacts of age and obesity." (PMID 40113928, 2025). "This justifies the optimal metabolic regulation among individuals with increased levels of prolactin and is also compatible with overweight and obesity documented among patients with hypoprolactinemia." (PMID 38826895, 2024). "It has been shown that administration of PRL via mini‐pumps attenuate IR and reduces inflammatory cytokines and retard adipocyte hypertrophy in visceral fat of diet‐induced obesity in rats." (PMID 39663784, 2024). "Clinical conditions that typically elevate prolactin or leptin levels, such as pregnancy, obesity, or treatment with antipsychotic drugs, have also been associated with an increased risk of thromboembolic events." (PMID 38255892, 2024). "Previous studies explored, among other factors, the effect of gender, age, obesity, and smoking on PRL levels." (PMID 39338159, 2024). "Studies on obesity and prolactin response are conflicting, showing either normal or decreased response." (PMID 39037546, 2024). "In these human studies, it seems that the relationship between leptin and prolactin is mediated by obesity, and the relationship between leptin and milk volume is mediated by prolactin." (PMID 39770967, 2024). "On the other hand, bromocriptine treatment, which is a dopamine agonist that lowers PRL levels, improves obesity, metabolic syndrome and cardiovascular parameters." (PMID 38700812, 2024). "The bioanalytical potential is demonstrated on tagged cell-penetrating peptides in vitro, and anti-obesity prolactin-releasing peptides in vivo." (PMID 39537622, 2024). "A study comparing prolactin excretion between normal-weight and women with overweight/obesity observed, after adjusting for confounders, that the prolactin response to suckling was lower in the overweight/obese women at days 2 and 7 postpartum." (PMID 39770967, 2024). "Age and obesity have been shown to potentially affect the peak prolactin response in the TRH stimulation test." (PMID 39037546, 2024).
Obesity (continued). "In women with obesity, two proposed mechanisms regarding prolactin action aim to explain its potential involvement in impaired lactation performance." (PMID 39770967, 2024). "Of note, upper‐limit PRL level within the physiological range seems to be a compensatory mechanism to mitigates inflammatory and oxidative stress as in obesity." (PMID 39663784, 2024). "Research on mice with obesity subjected to a high-fat diet has shown that leptin receptors are present in prolactin-responsive cells within both the mammary gland and the hypothalamus." (PMID 39770967, 2024). "A large population-based study from Florida, showed that women with overweight or obesity had a lower prolactin response to suckling." (PMID 38933819, 2024). "Lipidized Prolactin Releasing Peptide (LiPR) increases the number of neural stem cells and new neurons, establishing adult neurogenesis as a target of anti-obesity pharmacotherapy." (PMID 38177913, 2024). "Conversely, patients experiencing a metabolic challenge, such as obesity, who are unable to respond by increasing PRL levels are more prone to suffer from metabolic alterations than those able to upregulate their PRL levels." (PMID 38004264, 2023). "Maternal obesity: SCOPE women with obesity had lower PRL (−19%, [95% CI: 2 to 33%] p = 0.02), hPL (−21% [95% CI: 12 to 28%] p < 0.0001) and GH2 (−27%, [95% CI: 17 to 36%] p < 0.0001) compared to non-obese women." (PMID 37049394, 2023). "PRL are produced and secreted from human adipose tissue and PRL levels in obese adipose tissue are much reduced over lean subjects, indicating diminished autocrine and paracrine actions of PRL in obesity." (PMID 36993818, 2023). "Considering these aspects, our goal was, first, to compare metabolic parameters in early postpartum according to breastfeeding status and, second, to evaluate the potential mediation effect of PRL on these parameters in women with overweight/obesity and GDM." (PMID 37711904, 2023). "As discussed in paragraph 2.1.2, locally produced PRL is involved in the regulation of human adiposity and dysregulation leads to perpetuation of obesity." (PMID 36993818, 2023). "An invasive macroprolactinoma with an initial PRL level of 863 ng/ml, grade IV obesity (BMI of 51.5), and hypogonadotropic hypogonadism were diagnosed." (PMID 37404423, 2023). "The combined effects of maternal age and obesity on pregnancy hormones show that younger women with a healthy BMI had significantly higher PRL and hPL and lower GH2 in STOP compared to SCOPE." (PMID 37049394, 2023). "Limited evidence indicates that prenatal metabolic health predicts delayed onset of mammary secretory activation and mothers with obesity have a lower prolactin response." (PMID 36208911, 2023). "In cats, as well as in humans, high serum concentrations of PRL were shown to correlate positively with obesity." (PMID 37626804, 2023). "Conversely, patients experiencing a metabolic challenge, such as obesity, that are unable to respond by increasing PRL levels, are more prone to suffer from metabolic alterations than those upregulating their PRL levels." (PMID 36213259, 2022). "PRL excess is known to promote weight gain, obesity, metabolic syndrome, and impairment in gluco-insulinemic and lipid profiles, likely due to the suppression of physiologic dopaminergic tone." (PMID 36237192, 2022). "In contrast, patients with overweight and obesity (OW/OB) having elevated PRL levels show better metabolic profiles than BMI-matched patients with lower PRL values, to imply that elevated PRL is a mechanism dealing with metabolic challenge." (PMID 36213259, 2022). "The PRLR is present in AT from rodents and humans and PRL is secreted by human AT, while obesity decreases PRL release from human fat." (PMID 36213259, 2022).
Obesity (continued). "Intriguingly, even though the elevated serum prolactin levels were observed since the first month of age, obesity was of late onset, beginning mildly in 6-month-old female mice and culminating in morbid obesity from 10 months of age onward." (PMID 35757410, 2022). "Prolactin (PRL) levels are reduced in the circulation of rats with diabetes or obesity, and lower circulating levels of PRL correlate with increased prevalence of diabetes and a higher risk of metabolic alterations in the clinic." (PMID 33746901, 2021). "Through a network pharmacology analysis, the anti-obesity effect of hispidulin was predicted to act on estrogen, prolactin, Rap1, and PI3K-Akt signaling pathways by targeting AKT1, SRC, EGFR, and GSK3B." (PMID 34944408, 2021). "AKT1, SRC, EGFR, and GSK3B were identified as key anti-obesity target genes of hispidulin, and estrogen, prolactin, Rap1, and PI3K-Akt signaling pathways were predicted to be involved in the anti-obesity effects of hispidulin." (PMID 34944408, 2021). "PRL excess and functional blockade of dopaminergic tone are key mechanisms implied in the pathogenesis of weight gain and obesity frequently described in patients with prolactinomas." (PMID 34917030, 2021). "The key anti-obesity targets of hispidulin were primarily related to estrogen, prolactin, CEGF, and Rap1 signaling pathways." (PMID 34944408, 2021). "Apolipoprotein A-I (apoA-I), melanocortin-4 receptor (MC4R)-specific agonist, GLP-1 dual and triple agonists, neuropeptides and prolactin-releasing peptide mimetics were specifically examined for their anti-obesity role." (PMID 30834248, 2019). "Menstrual disorders and visual field defects were more common in patients in the CD + PRL group (compared with the CD group), whereas the incidences of progressive obesity and hypertension were much lower." (PMID 25506361, 2014). ", whereas the incidences of progressive obesity and hypertension were much lower in patients in the CD + PRL group than in patients in the CD group (P = 0.009 and P < 0.001, resp)." (PMID 25506361, 2014). "These alterations seem to be due to obesity per se with its hyperinsulinaemic state as well as an interplay between PRL and leptin concentrations." (PMID 20182553, 2010). "Emerging evidence indicates that prolactin is involved in energy homeostasis and may interact pathophysiologically with obesity; this has attracted increasing attention in endocrinology and metabolic research." (PMID 41918976, 2026). "Furthermore, prolactin is a lipogenic hormone, and elevated levels can result in obesity, subsequently impacting peripheral insulin sensitivity." (PMID 40362476, 2025). "In mothers with obesity, prolonged inflammation within the mammary gland, a blunted hormonal response (notably of prolactin), altered progesterone and estrogen dynamics, high leptin levels, and misaligned circadian rhythms contribute significantly to delayed lactogenesis." (PMID 40868103, 2025). "However, multiple studies have indicated that mothers with obesity exhibit a provoked lower prolactin response to suckling in the early postpartum period." (PMID 40868103, 2025). "Several studies have indicated that sleep disorders in prolactinoma patients are not directly related to prolactin levels, and they suggest that obesity and higher BMI are associated with sleep disorders in prolactinoma patients." (PMID 38572480, 2024). "The authors’ conclude that DAs could potentially explain the weight loss alongside the metabolic advantages observed, stressing the importance of specifically screening prolactin (PRL) levels in men dealing with severe obesity." (PMID 38510701, 2024). "Therefore, normal physiological PRL level seems beneficial against IR, obesity and development of MetS." (PMID 39663784, 2024). "Thus, restoration of normal PRL levels by dopaminergic agonists has been suggested by different studies to be substantial in the management of obesity." (PMID 39663784, 2024).